CCL3 (C-C motif chemokine ligand 3)
Diseases named in the same sentence as CCL3 in open-access papers (continued):
Sharing a sentence is not in itself a finding about the gene and the disease.
infection (continued). "Importantly, neutrophil-depletion abrogated CCL3’s beneficial effects in boosting antimicrobial defenses against P. aeruginosa in diabetic wounds, indicating that CCL3-induced enhanced infection control in diabetic wound is dependent on its ability to enhance neutrophil response in diabetic wound." (PMID 35112667, 2022). "Microglia also express additional subsets of chemokines (Ccl2, Ccl3, Ccl4) with no overlap to those detected in vascular-associated cells, potentially indicating non-redundant mechanisms of T cell recruitment into the brain parenchyma during infection." (PMID 36180478, 2022). "Since we had observed production of higher levels of CCL3 and not the CCL4 and CCL5 chemokines by LdCen-/ -infected neutrophils, we therefore assessed whether chemo-attractive activity of CCL3 itself is necessary and sufficient to explain the elevated DC migration observed in LdCen-/- infection." (PMID 35192633, 2022). "Thus, our data support that CCL3 may act dualistically, in the acute infection controlling parasite growth and in the chronic phase facilitating, direct or indirectly, heart parasitism." (PMID 32194558, 2020). "However, CCL3 was increased by LOAd infection, except in RPMI-8226 cells." (PMID 32355275, 2020). "Our observed association between initial elevation of serum CCL3 levels and infiltration of monocytes in Junbo mice middle ears with no NTHi infection suggests it could play a role in defence against NTHi infection in pre‐inflamed middle ears." (PMID 30265765, 2019). "Likewise, brain tissues of animals with S. epidermidis-infected catheters had higher levels of IL-10 (P < 0.001), IL-1β (P < 0.001), CCL2 (P < 0.001), and CCL3 (P < 0.001) at day 1 postinfection, demonstrating that the CSF inflammatory milieu mirrors that of the brain tissue during early infection." (PMID 31262978, 2019). "Therefore, IL-1β, CCL2, and CCL3 may be useful biomarkers for tracking infection and determining when antibiotic treatment could be terminated as well as for diagnosis, although additional studies are needed to validate this possibility." (PMID 31262978, 2019). "Over the course of infection, genome amplification correlated with increases in expression of two of the six bat host genes tested including CD80, a DC activation marker associated with T-cell priming, and CCL3, a potent chemokine produced by APCs upon stimulation with LPS." (PMID 31681302, 2019). "Finally, the neutrophil recruitment after rHMPV-ΔG infection could have also been altered by the reduced expression of CCL3 and CCL4, which are neutrophil-active chemokines." (PMID 29065494, 2017). "At times early following infection, multiple transcripts encoding proinflammatory molecules were increased, including IL8 (8196-fold), IL1B (1559-fold), oncostatin M (OSM, 799-fold), CCR1 (588-fold), CXCR1 (625-fold), CXCR2 (596-fold), CCL4 (514-fold), and CCL3 (658-fold)." (PMID 25719526, 2015). "Therefore, studies evaluating CCL3 mRNA and protein accumulation at later stages during infection may be complicated by secretion of other mediators and by the accumulation of viral gene-products that selectively interfere with innate immune responses." (PMID 23062757, 2012). "Altogether, we identified a novel role for neutrophil-secreted CCL3 in the first wave of DC recruitment to the site of infection with L. major, suggesting that the selective release of neutrophil-secreted chemokines may regulate the development of immune response to pathogens." (PMID 20140197, 2010). "Infection of rhesus (Macaca mulatta) or cynomolgus (Macaca fascicularis) macaques with pathogenic SIV leads to the induction of multiple inflammatory chemokines in lymph nodes and spleen including: CXCL8; CXCL9, CXCL10, and CXCL11; CCL3, CCL4, CCL5; CCL2; CCL19; and CCL20." (PMID 19149556, 2009). "Secreted CCL3, CCL4, CCL5, CXCL10, IFN-γ, IL-10, and VEGF were also significantly elevated in LCLs but at lower levels than in de novo infection." (PMID 40359016, 2025).
infection (continued). "Greater CCL5 activity was predicted in C57BL/6 mice at 20 days after infection, whereas predicted activity of the chemokines CCL6, CCL9, CCL3, and CCL4 was highest in C3HeB/FeJ mice by 20 days after infection." (PMID 40986319, 2025). "Infection also boosted the expression of the CXCL2, CCL2, CCL3, and CCL5 chemokines in female mice, while only CCL2 and CCL3 expression increased in males." (PMID 40143355, 2025). "Consistently, the LASSO regression retained five of these six parameters as the strongest predictors of infection status: urea (coefficient = 0.41), IL-10 (0.53), TNF (0.49), CCL3 (0.38), and IL-1β (0.33)." (PMID 41279035, 2025). "Inflammatory chemokines, such as IL‐8, MIP‐1α/CCL3, and MIP‐3α/CCL‐20, act mainly by attracting monocytes, neutrophils, and other effector cells from the blood to sites of infection or tissue damage." (PMID 40101934, 2025). "The data revealed that NK cell-mediated modulation of CCR5 expression on DCs, along with the production of chemokines CCL3 and CCL5 in the lungs, contributed to DCs recruitment to infection sites." (PMID 40332391, 2025). "Like PMs, THP-1 cells also produced IL-6, CCL4, CCL2, IL-1RA, CCL3, and CXCL9 upon infection with the RSV strain A-0594, although the peak of these responses differed in some cases." (PMID 41280933, 2025). "For this, we measured the quantity of CCL3, CCL5, and CCL4 in the culture supernatants of macrophages infected with HIV and treated with P3DEX or DEX at 24, 48, and 72 h post infection." (PMID 40077760, 2025). "In lung tissue, IL1B, IL6, IL10, CXCL2, CCL3 and CCL5 levels also rose in both genotypes following infection, although these markers were significantly lower in TLR7 KO mice." (PMID 40442368, 2025). "We found that infection of PBMC by the neurovirulent HIV-1ADA and treatment of PBMC by recombinant Tat of HIV-1YU-2 strain, both up-regulated chemokines CCL-2, CCL-3, and CCL-4 to significant levels." (PMID 40313367, 2025). "On the other hand, infection with SFV/TNFα specifically upregulated the amount of IL-6, CCL2, CCL3, CCL7 and CCL20 (p < 0.0001)." (PMID 40547518, 2025). "We noted that infection in female TLR7ko mice boosted IFNG, CCL2, CCL3, and CCL5 expression, although significantly less compared to the female WT group, but these responses were completely blunted in TLR7ko male mice." (PMID 40143355, 2025). "CCL-3 and CXCL-8 are chemokines that attract macrophages and neutrophils, respectively, which can increase inflammation at the infection site to eliminate ETEC." (PMID 40619401, 2025). "Infection upregulates proinflammatory cytokines such as TNF-α and IFN-γ and chemokines such as CCL2/MCP-1, CCL3/MIP-1α, and CCL5/RANTES, while downregulating the astrocytic glutamate transporter, GLT-1." (PMID 40743275, 2025). "The chemokine CCL3 and its receptor CCR1 were upregulated 10.5- and two-fold, respectively, by the infection." (PMID 41398915, 2025). "IL-8 and CCL3 were produced at significantly increased levels compared to mock infection, with trends for IL-6, CXCL1, and CXCL10, at 12 h post-infection." (PMID 39599904, 2024). "The inflammatory cytokines TNFα, IL-4, IL-6, IL-13, IL-10, IL-12 (P40), and IL-12 (P70) along with chemokines including CCL2, CCL3, and CCL5, were significantly elevated in the plasma of c-Flip+/–mice on day 2 post-infection compared that of WT mice." (PMID 39038037, 2024). "We observed that concentrations of the monocyte chemoattractants CCL2, CCL3, CCL4, CCL5, and CCL7 were significantly increased in mice inoculated with both pathogens, relative to vehicle and single Bb infection." (PMID 39229265, 2024). "CC chemokines have been shown to play an important role in inflammation, as both CCL3 and CCL4 orchestrate the immune responses to infection or inflammation." (PMID 39058144, 2024).
infection (continued). "Spinal cords of wild-type mice contained significantly higher levels of IFN-β and IL-6 at day 5 post-infection (p ≤ 0.05) and IFN-γ, IL-1β, CCL3, CCL5, and CXCL9 at 5 and 9 days post-infection (p ≤ 0.05)." (PMID 39339840, 2024). "Significant decreases in CCL3, CCL4, and CXCL2 were observed in the galea of TNF KO mice at day 14 post-infection, corresponding to the timepoint and anatomical location where granulocyte recruitment was maximally reduced." (PMID 39044282, 2024). "We also analyzed the expression of chemokines CCL2, CCL3, and CCL4, which are synthesized in response to infection and play an important role in the recruitment of monocytes/macrophages to inflammation sites." (PMID 38674602, 2024). "By bonding with particular chemokines, such as CCL3, CCL4, CCL5, CCR1 facilitates cell chemotaxis, directing immune cell migration towards inflammatory or infection sites, a function vital for initiating and modulating immune responses." (PMID 39931101, 2024). "T cells secrete numerous chemokines including CCL2, CCL3, and CCL4, which direct cellular recruitment to the site of infection." (PMID 38977711, 2024). "For a subset of patients, we assessed chemokines (CCL2, CCL3, and CCL7) in circulation and at the site of infection." (PMID 36752598, 2023). "Differences between ZIKV strains and DENV and YFV-17D were particularly evident for CCL-3, IP-10, IFN-2α, and IFN-γ, suggesting that in HTR8 cells, the infection with ZIKV inhibits the production of chemoattractant and recruiting chemokines as well as IFNs." (PMID 37227282, 2023). "Infection with both ZIKV lineages was characterized by a more proinflammatory and chemotactic profile, mediated by high levels of IL-1β, IL-6, TNF-α, CCL-2, CCL-3, CCL-7, CXCL8, IP-10, and VEGF." (PMID 37227282, 2023). "The expressions of CCR5 (the receptor of CCL3, CCL4, and CCL5) and CCRL2 (expressed on neutrophils and primary monocytes) were significantly down-regulated by the WT infection." (PMID 37513744, 2023). "Compared to B lineage isolates, infection of mice with UT21 had lower levels of CCL2, CCL3, CCL4, TNF-α, and IL-1β." (PMID 36992320, 2023). "Upon infection with influenza viruses, CCR5 and its cognate chemokines CCL3, CCL4, and CCL5 are induced rapidly, which contributes to leukocyte recruitment into the airways and a consequent efficacious antiviral response." (PMID 37041527, 2023). "CCL3-mediated chemotaxis has also been noted to influence the migration and function of CD8+ T cells to sites of infection following RSV exposure." (PMID 37795093, 2023). "Infection with this bacterium was shown to increase the production of IFN-γ, TNF-α, and chemokines such as CCL3, CCL4, CCL5, CCL11, and CXCL1." (PMID 38139161, 2023). "At day 6 after infection, expression levels of chemokines, including CXCL10 and CCL2 and CCL-3 were elevated by more than 300-fold." (PMID 35215199, 2022). "Consistent with higher macrophage activation due to Erdman relative to CDC1551 infection, BAL and plasma concentrations of MIP1-α (macrophage inflammatory protein 1-alpha) also known as CCL3 (C-C motif ligand 3) were higher in the Erdman group at necropsy." (PMID 35412961, 2022). "There was a significant increase in mRNA expression of macrophage and neutrophil chemotactic factors CXCL10, CCL3, CXCL1 (KC) and CXCL2 in the lungs of IAV-infected WT mice 3-days post infection." (PMID 35601109, 2022). "From the present investigation, we found the expression of IL-1β, CXCL10/IP-10 and CCL3/MIP-α increased in the blood and most organs day by day as the infection progressed." (PMID 35584087, 2022). "Expression of macrophage and neutrophil chemoattractants CXCL10, CCL3, CXCL1 and CXCL2 in the lung tissue were significantly lower in NOX4 TG mice compared to the WT mice at 3-days post infection." (PMID 35601109, 2022).
infection (continued). "The proinflammatory chemokines CCL3, CXCL3, and CXCL10 were also upregulated following infection, while synapse-related genes, including C1QL1 and SYPL1, were downregulated." (PMID 36314791, 2022). "Proinflammatory cytokines associated with Th17/Th1 response such as IL-6, TNF-α, and IL-1β, and neutrophil-recruiting chemokines including CCL2, CCL3, CXCL1, and CXCL2 were highly produced from day 3 to day 14 after WT infection." (PMID 35696422, 2022). "The reduction of the mRNA expression of CCL2, CCL3, FGF, CXCL-10, and IFN-γ at the 9th-week post-infection reflects a downmodulation of the Th1 response by reducing the recruitment of inflammatory cells and HSCs to the granulomatous site." (PMID 35839247, 2022). "Filaggrin, MIP-1α/CCL3 and MCP-1 levels were higher in pre-infection supernatants compared to controls." (PMID 36482106, 2022). "It is reported that the infection of microsporidia Encephalitozoon cuniculi up-regulated expression of CCL1, CCL2, CCL3, CCL7 and other chemokines." (PMID 36015036, 2022). "In some patients, we were even able to detect an increase in certain cytokines, such as CCL3 or CCL4, 33 days after the suspected date of infection (Figure A3)." (PMID 35458486, 2022). "In response to ocular HSV-1 infection, pro-inflammatory cytokines including IL-1, IL-6 and chemokines including CCL2, CCL3, CCL5, CXCL1, CXCL2, CXCL9, and CXCL10 are produced rapidly following infection by resident cells and infiltrating leukocytes." (PMID 36685562, 2022). "We found the levels of CXCL1, IL-6, IL-1β, CCL3 and CCL4 were higher in the kidney homogenates of female mice infected with the eng1 strain at days 1 and 4 post-infection in comparison to that infected with the ENG1 strain." (PMID 34995333, 2022). "Lenti-Spike infection significantly increased the expression of inflammatory cytokines, including IL-1β, IL-6, and TNF-α, and chemokines, including CCL-2, CCL-3, CCL-4, and CXCL-10, whereas Lipo-hACE2 decoy significantly inhibited all these effects." (PMID 35401811, 2022). "The expression levels of CCL3, CCL5, CXCL10 and CX3CL1 in the brain tissue of infected mice was elevated with the extension of infection time." (PMID 34017692, 2021). "There were some cytokine transcripts differentially expressed early in infection (IL6, CXCL10, and CCL3 for example), but overall only a minority of DEGs are cytokines (n = 13)." (PMID 34615921, 2021). "The infection and fatal groups showed considerable increases in several inflammatory factors (gamma interferon [IFN-γ], interleukin 6 [IL-6], IL-8, SIRT2, CCL3, and CXCL10) compared to the control group." (PMID 33593977, 2021). "Neutrophils provide the chemical cues (MCP-1/CCL2, MIP-1α/CCL3, MIP-1β/CCL4 and MIP-2/CXCL2) that help recruit macrophages to the infection site." (PMID 34712235, 2021). "Monocyte chemotactic protein 1 (MCP1 or CCL2), macrophage inflammatory protein 1 (MIP-1α or CCL3), and MIP-1β (CCL4) are crucial for macrophage migration/invasion and immune responses toward infection and inflammation." (PMID 33748112, 2021). "Particularly, infection upregulated the cytokines IFN-γ, IL-12b, and IL-2 (126-, 44-, and 18-fold change, respectively) and the T-cell chemoattractants CCL3 and CCL5 (23- and 16-fold change, respectively)." (PMID 34381739, 2021). "The extracellular version of protein Nef expressed in the early phase of infection of the human immunodeficiency virus (HIV) triggered the release of CXCL8/IL-8 and CCL3/MIP-1α through the CXCR4 receptor in MCs." (PMID 34211473, 2021). "Several chemokines potentially attract neutrophils during an infection and S. suis infection induces the production of many of them, such as CXCL1 (KC), CXCL2 (MIP-2), CCL2 (MCP-1), CCL3 (MIP-1α), CCL4 (MIP-1β) and CCL5 (RANTES)." (PMID 34835517, 2021).
infection (continued). "Overall, modestly downregulated genes in the human BSC were genes involved in chemotaxis and recruitment of infiltrating leukocytes (CCL3, CXCL16) suggesting that RABV suppresses recruitment of infiltrating immune cells to the site of infection." (PMID 34804996, 2021). "Chimeras were immunized with Lm-gB and treated with DT before Lm-gB challenge infection, and we monitored both LLO91–99/Kd and gB498–505/Kb Tet+ CD8+ TM cells for Ag-dependent chemokine (CCL3) and Ag-independent IFNγ production." (PMID 34516896, 2021). "Several chemokines were induced quickly in the early phase (day 2 p.i.)and maintained at a rather high level through the first week of infection, including CCL2, CCL3, CCL4, CCL7, CXCL10, IL-6, IFN-γ, CCL11, CCL5, TNF-α, CXCL1, IL-4, IL-12p70." (PMID 34379705, 2021). "Pneumocystis infection appears to be associated with dysfunction of the IL-23/IL-17 axis, with higher lung fungal burdens and reduced production of IL-17 and chemokines CXCL10 (IP-10), CCL3, CCL4, and CCL5, all crucial for infection resolution." (PMID 34829225, 2021). "(E) Recovery of GFP-positive CEM-GXR cells following blocking of restriction factors (CCL3/4/5), after treatment with IL12/18 stimulated supernatant from CD8 cells and infection with HIVBAL." (PMID 34951583, 2021). "VSV infection significantly induced the expression of seven chemokines (CCL3, CCL4, CCL5, CCL20, CXCL1, CXCL2, and CXCL3) by ~3- to 42-fold compared to mock infection." (PMID 34578166, 2021). "The chemotactic cytokines called macrophage inflammatory proteins (MIPs) include MIP-1α (also called CCL3) and MIP-1β (also called CCL4), which orchestrate immune responses to infection and inflammation." (PMID 32751118, 2020). "For example, high levels of CXCL-10/IP-10, CCL-2/MCP-1, CXCL-5/RANTES, and CCL-3/MIP-1α enhance the recruitment of dendritic cells and macrophages to the site of infection." (PMID 32922406, 2020). "Previous in vivo studies following experimental infection with Ab4-wt (neuropathogenic) strain showed release of fewer cytokines/chemokines at low concentration (IL-10, CCL2, CCL3) in comparison to RacL11 and NY03 strains (abortigenic strains)." (PMID 32911663, 2020). "Then, we showed a lower level of CXCL1 and CCL3 in TLR-2KO and TLR-4KO peritoneal lavage, suggesting that TLR-2 and TLR-4 are important to chemokine production by resident cells in the infection site." (PMID 33193308, 2020). "Several chemokines, including IP-10 (CXCL10), CCL2 (MCP-1), CCL3 (MIP-1α), CCL4 (MIP-1β), CCL5 (RANTES), and CCL7 (MCP-3) were also significantly increased upon infection." (PMID 32373101, 2020). "Levels of IL-1β, IL-6, CCL2, CCL3, CXCL1, and CXCL2 were significantly greater 6 h following infection than in mock-infected mice (P < 0.05) but were similar among wild-type, CCR2−/−, and Nr4a1−/− mice." (PMID 31818962, 2020). "Regarding to the role of chemokines, has been reported that elevated concentrations of CCL3 and CCL5 at day one post-infection are consistent with recruitment of monocytes and lymphocytes into the mice lungs." (PMID 30936869, 2019). "In the immunocompetent mice, the Chr6ABB strain induced significantly less CCL3, CXCL1 (KC), IL-1β, IL-17A, and the p19 subunit of IL-23 in the oral tissues relative to the progenitor strain after 1 day of infection." (PMID 31091232, 2019). "A single unilateral injection of EcoHIV (1 × 106 pg) directly into the caudate putamen resulted in a significant increase in inflammatory markers (TNFα, IL-1β, IFNγ, CCL2, CCL3, CXCL10) 5 days after infection." (PMID 31263138, 2019). "Herein, a single unilateral injection of EcoHIV (1 × 106 pg) directly into the caudate putamen resulted in a significant increase in inflammatory markers TNFα, IL-1β, IFNγ, CCL2, CCL3 and CXCL10 5 days after infection." (PMID 31263138, 2019). "The protein levels of CCL2, CCL3, CCL4, and CCL5 in the liver of μMT mice 6 weeks after infection were significantly increased compared with those of WT mice." (PMID 31194740, 2019).